RNU1-142P (RNA, U1 small nuclear 142, pseudogene)
Gene: Small nuclear RNA gene on chromosome X (26,790,142 to 26,790,286, forward strand). Ensembl gene ENSG00000252491.
Homologues: Orthologues: chimpanzee U1 (97% identical), macaque U1 (94% identical), rabbit RNU1-142P (63% identical), pig U1 (59% identical), rat U1 (57% identical), guinea pig U1 (54% identical), mouse Gm25115 (50% identical). Paralogues in human: RNU1-67P (70% identical), RNU1-1 (70% identical), RNU1-11P (70% identical), RNU1-2 (70% identical), RNU1-27P (70% identical), RNU1-28P (70% identical), RNU1-3 (70% identical), RNU1-4 (70% identical), RNU1-63P (70% identical), RNU1-89P (70% identical), RNVU1-18 (70% identical), RNVU1-28 (70% identical), and 133 more.